PTH (parathyroid hormone)
Diseases named in the same sentence as PTH in open-access papers (continued):
Sharing a sentence is not in itself a finding about the gene and the disease.
Albright hereditary osteodystrophy (27 papers, 2010 to 2026). "Albright's hereditary osteodystrophy is a rare disease, characterized by phosphocalcic balance abnormalities related to peripheral resistance to parathyroid hormone." (PMID 32180864, 2019). "Differential diagnosis should not only include the different subtypes of acrodysostosis but also other entities of the “inactivating PTH/PTHrP signalling disorders” that clinically present with Albright hereditary osteodystrophy (AHO)." (PMID 28515031, 2017). "In both conditions there is resistance to parathyroid hormone but PHP-Ia is also associated with multiple hormone resistance and Albright hereditary osteodystrophy (AHO)." (PMID 23822972, 2013). "PHP is characterized by resistance to parathyroid hormone (PTH) and Albright hereditary osteodystrophy (AHO)." (PMID 41153459, 2025). "Human diseases associated with the GNAS gene encompass fibrous dysplasia (FD), Albright’s Hereditary Osteodystrophy (AHO), parathyroid hormone(PTH) resistance, and Progressive Osseous Heteroplasia (POH), among others." (PMID 37920253, 2023). "Patients with PHP1a predominantly exhibit parathyroid hormone (PTH) resistance and physical features of Albright's hereditary osteodystrophy." (PMID 35497370, 2022). "PHP1A is the clinical entity characterized by resistance to multiple hormones, mainly PTH and TSH, with features of Albright hereditary osteodystrophy (AHO)." (PMID 31555217, 2019). "Patients are resistant to the action of PTH and TSH in the absence of additional clinical features, although a subset of patients also presents physical features of Albright hereditary osteodystrophy." (PMID 30616679, 2019). "Pseudohypoparathyroidism type 1b (PHP-Ib) is characterized by renal resistance to PTH (and, sometimes, a mild resistance to TSH) and absence of any features of Albright's hereditary osteodystrophy." (PMID 25710380, 2015). "BDMR could be misdiagnosed as Albright hereditary osteodystrophy (AHO), because it presents with lack of hormone resistance to parathyroid hormone (PTH) and similar skeletal and craniofacial abnormalities; however, BDMR is far rarer and can present with a different phenotype." (PMID 30357083, 2018).
Hypocalciuria (27 papers, 2013 to 2026). An abnormally decreased calcium concentration in the urine. "These include serum calcium levels that range from slightly to significantly elevated, PTH levels that are high-normal to elevated, normal phosphate levels, hypermagnesemia, and hypocalciuria." (PMID 40182382, 2025). "We would like to mention that among the two patients with PTH hypersecretion, both of them had hypocalciuria (<100 mg/day), they were both male, one was a patient with UC, while another one was affected with CD." (PMID 35407448, 2022). "Patient CA106 is a 39-year-old male who was referred for evaluation of elevated serum Ca2+ and PTH levels in several routine blood laboratory analyses and hypocalciuria." (PMID 32997713, 2020). "In our cohort, two patients (CA106 and SOR171) presented with elevated serum Ca+ and PTH levels and hypocalciuria." (PMID 32997713, 2020). "In addition to hypocalciuria, increased PTH and the an ultimately slightly elevated serum calcium eventually led to consideration of FHH." (PMID 28690912, 2017). "The observation of higher serum levels of PTH and 1,25(OH)2D in untreated CeD also implied the possibility that the stimulatory effects of PTH and 1,25(OH)2D on kidney tubule Ca reabsorption were the true determinants of the relative hypocalciuria classically reported in CeD." (PMID 32230847, 2020).
prostate carcinoma (27 papers, 2001 to 2025). A carcinoma that arises from epithelial cells of the prostate gland. "Prostate cancer progression and mortality are associated with changes in calcium metabolism, parathyroid hormone levels, vitamin D levels, and androgen signaling." (PMID 35063506, 2022). "Previous studies have showed that high serum PTH was common in prostate cancer patients and was inversely associated with mortality." (PMID 30013512, 2018). "Increased proliferation and chemotaxis of prostate cancer cell lines have been linked with binding of PTH to these receptors." (PMID 23606986, 2013). "However, as for romosozumab, use of PTH analogues in men with prostate cancer undergoing ADT remains off‐label due to a theoretical risk of stimulating growth of occult bone metastases." (PMID 40357899, 2025). "It has been previously hypothesized that high serum Ca or PTH increase, is a risk factor for fatal prostate cancer." (PMID 28284204, 2017). "In several studies investigating the relationship between Ca intake and the risk of developing aggressive or clinically relevant prostate cancers as well as the relationship between prostate disorders, PTH and vitamin D have both generated null and positive results." (PMID 28284204, 2017). "Among prostate cancer patients, vitamin D levels correlated positively with age (r = 0.12, P < 0.02), and were negatively associated with BMI (r = −0.13, P = 0.003), glucose (r = −0.12, P < 0.007), HbA1C (r = −0.16, P = 0.001), and PTH (r = −0.21; P < 0.0001)." (PMID 23304521, 2012). "PTH and PTH-like proteins are seemingly both a predictive factor for prostate cancer and an aggressivity-inducing feature when prostate cancer is already present." (PMID 39200986, 2024). "It is not only responsible for maintaining calcium hemostasis by regulation of the parathyroid hormone, but also appears to play a crucial role in the development of bone metastases in several cancers such as breast and prostate cancer." (PMID 29644008, 2018). "ADT does not have a significant impact on serum calcium, 25-hydroxyvitamin D, or PTH, but epidemiological studies have suggested that high levels of calcium intake may suppress PTH and ultimately 1,25-dihydroxyvitamin D and associated with increased risk of prostate cancer." (PMID 20482867, 2010). "Meanwhile, PTH has been shown to increase cell proliferation of human prostate cancer in vitro and to promote bone metastasis in mouse xenograft model of prostate cancer." (PMID 19602280, 2009). "PTH level was slightly increased in bone metastatic patients compared to healthy controls, according to PTH ability to promote the growth and invasiveness of prostate cancer cells in bone." (PMID 18978943, 2008). "Others have also reported that parathyroid hormone injection in athymic mice induced a preferential localisation of PC-3 prostate cancer cells in bones." (PMID 18253114, 2008). "Athymic mice were treated with recombinant parathyroid hormone (PTH), a well-known stimulator of bone turnover, inoculated mice with prostate cancer cells, and found that mice treated with PTH had increased bone formation adjacent to tumor regions compared to control mice." (PMID 31330786, 2019). "Previous studies in prostate cancer models have reported that in animals with subcutaneous tumours receiving a daily administration of PTH for three weeks, increased numbers of tumour cells were recovered from the mandible, rib, spine and tibia, but not from femurs, compared to control." (PMID 30261597, 2018). "Our results seem to support the last hypothesis because a stronger PTH-rP-specific cytolytic response to prostate carcinoma LNCaP cells was observed in CTL lines derived from spleen cells taken from mice receiving the sequential GC90/IRIV/peptide treatment." (PMID 12838324, 2003). "A PTH increase and thus a parallel Ca rise is in some way connected to or induced by prostate cancer, without the presence of any clinical bone metastases." (PMID 39200986, 2024).
prostate carcinoma (continued). "In the combined analysis of vitamin D in all subjects (with and without prostate cancer), we observed significant negative correlations between vitamin D levels and BMI (r = −0.11; P < 0.0005) and PTH levels (r = −0.26; P < 0.0001)." (PMID 23304521, 2012). "Therefore, reducing PTH secretion could potentially interrupt SHPT and be of substantial clinical benefit in prostate cancer patients." (PMID 19602280, 2009).
cardiac hypertrophy (26 papers, 2013 to 2025). "There is an association between PTH levels, myocardial hypertrophy, and mortality, in patients with sHPT and in individuals from the general population." (PMID 32192220, 2020). "Association of PTH with myocardial hypertrophy, fibrosis and higher coronary lesion score was described in animal model." (PMID 23844967, 2013). "In experimental studies using a rat model of CKD (5/6 nephrectomy) submitted to PTX, the continuous infusion of supraphysiological rates of 1–34 PTH was associated with myocardial hypertrophy and fibrosis along with a high myocardial expression of oxidative stress and inflammation markers." (PMID 32192220, 2020). "Experimental models surmise that calcium release triggered by excess PTH results in increased protein kinase C activity, leading to myocardial hypertrophy." (PMID 36751183, 2023). "Previous studies demonstrated that FGF23 inhibited parathyroid hormone secretion through MAPK pathway or induced myocardial hypertrophy mediated by activation of PLCγ-calcineurin-NFAT pathway." (PMID 33460402, 2021). "Elevated PTH levels can increase production of collagen by vascular smooth muscle cells and directly affect cardiac function, reducing contractility and inducing ventricular hypertrophy." (PMID 29751781, 2018). "Numerous studies have identified that high sodium intake and elevated levels of PTH are independent risk factors for myocardial hypertrophy, irrespective of their role in blood pressure regulation." (PMID 37842376, 2023). "Indeed, intact parathyroid hormone (iPTH) has a direct trophic effect on cardiomyocytes and fibroblasts, leading to intramyocardial arterial wall thickening, ventricular hypertrophy, and myocardial fibrosis." (PMID 37779359, 2023). "However, our study confirms that high salt intake and PTH can interact in Sprague-Dawley rats to produce a synergistic effect, resulting in pathological changes such as myocardial hypertrophy and myocardial fibrosis in a short period." (PMID 37842376, 2023). "Moreover, cardiac hypertrophy is caused by vascular calcification and excess FGF23 secretion related to uncontrolled SHPT and excess PTH induces cachexia." (PMID 36512619, 2022). "In addition, we used neonatal rat ventricular myocytes (NRVM) to study the role of parameters of altered mineral metabolism including calcium, phosphate, PTH, and 1,25D for the induction of cardiac hypertrophy." (PMID 29977226, 2018). "Excessive levels of PTH result in ventricular hypertrophy, cardiac calcification, and fibrosis." (PMID 28596785, 2017). "Given that parathyroid hormone induces cardiac hypertrophy via its receptor on myocytes, its signal may influence glycosylation within cardiac myocytes and thus the glycoNT-proBNP/nonglycoNT-proBNP ratio." (PMID 24667631, 2014). "Serum levels of parathyroid hormone (PTH), which has bbe shown to be correlated with UA, is also known to be associated with cardiac hypertrophy; however, whether the association between UA and cardiac hypertrophy is independent of PTH remains unknown." (PMID 24340056, 2013). "Furthermore, PTH induces myocardial dysfunction and cardiac hypertrophy." (PMID 34044733, 2021). "PTH might indirectly induce myocardial hypertrophy by increasing FGF-23 synthesis." (PMID 32192220, 2020). "Particularly, it provides evidence that CKD-associated cardiac hypertrophy correlates with reduced eGFR and soluble Klotho and Vitamin D levels, and is indicative of a generalized pro-inflammatory status, as evidenced by increased levels of IL-6, ACR, PTH, P and FGF23." (PMID 30934737, 2019). "Nevertheless, to the best of our knowledge it seems that whether the relationship between serum UA and cardiac hypertrophy, when present, is dependent or independent of serum PTH has not been examined." (PMID 24340056, 2013).
hyperuricemia (24 papers, 2012 to 2025). An abnormally high level of uric acid. "Hyperhomocysteinemia, hyperuricemia, hypoproteinemia, hyper-phosphatemia, methylmalonic acidemia, increased PTH, and serum osmolality level were significantly associated with CKD in prior studies 19-25." (PMID 36438912, 2022). "A strong association of sUA with renal function and PTH limits a clinical assessment of hyperuricemia." (PMID 34362049, 2021). "By using data from 8316 participants, authors proved that serum PTH levels are independently associated with sUA levels and the frequency of hyperuricemia at the population level." (PMID 34362049, 2021). "The association between VDD and hyperuricemia can be postulated by UA inhibition of hepatic 25-hydroxylation or PTH-induced ABCG2 down-regulation in the intestine and proximal renal tubules, which results in hyperuricemia." (PMID 31491937, 2019). "These nationally representative data indicate that serum PTH levels are independently associated with serum uric acid levels and the frequency of hyperuricemia at the general population level." (PMID 22405053, 2012). "These nationally representative data indicate that serum PTH levels are independently associated with serum uric acid levels and the frequency of hyperuricemia at the population level." (PMID 22405053, 2012). "Furthermore, recent randomized controlled trials have also found that hyperuricemia or gout is associated with use of teriparatride, a recombinant human PTH approved for osteoporotic fracture prevention." (PMID 22405053, 2012). "Earlier population-based studies (largely using mixed or male-dominant cohorts) have consistently reported that individuals with higher PTH also possess enhanced UA levels, and, therefore, experience greater odds of hyperuricemia." (PMID 41169475, 2025). "Conversely, hyperuricemia is drastically reduced after parathyroidectomy, reinforcing the suggested link between PTH and UA balance." (PMID 39768960, 2024). "Previous studies found that PTH increased the incidence of hyperuricemia in a dose–response fashion." (PMID 36583002, 2022). "Given our observations, one has to take into consideration not only GFR, but also PTH when assessing hyperuricemia." (PMID 34362049, 2021). "A nationally representative population study among 8,316 participants, from the US and male and female, indicated that serum uric acid levels and the frequency of hyperuricemia increased with increasing parathyroid hormone levels." (PMID 33330592, 2020). "Previous clinical trials of 1,637 postmenopausal women found that parathyroid hormone increased the incidence of hyperuricemia in a dose-response fashion, and serum uric acid levels decrease after cessation of treatment." (PMID 33330592, 2020). "In a cross-sectional study, the serum PTH level was positively correlated with serum UA level, and the PTH level was significantly higher in patients with hyperuricemia than normouricemia." (PMID 31491937, 2019). "Previous clinical trials of postmenopausal women found that parathyroid hormone increased the incidence of hyperuricemia in a dose-response fashion." (PMID 23585876, 2013). "A previous clinical trial in postmenopausal women indicated that parathyroid hormone increased the incidence of hyperuricemia." (PMID 23585876, 2013). "In our nationally representative population study of US men and women, we found that serum uric acid levels and the frequency of hyperuricemia increased with increasing PTH levels in a graded manner." (PMID 22405053, 2012). "The odds of hyperuricemia by various definitions increased with increasing PTH levels as well (multivariate P values for trend, < 0.05)." (PMID 22405053, 2012). "For example, the multivariate odds ratios (ORs) for hyperuricemia according to increasing quintiles of serum PTH level were 1, 1.07, 1.22, 1.36, and 1.39 (95% CI, 1.03 to 1.88; P for trend = 0.03)." (PMID 22405053, 2012).
hyperuricemia (continued). "Additionally, the antiosteoporosis agent teriparatide, a recombinant PTH, has been found to promote hyperuricemia in a dose-dependent manner in post-menopausal women." (PMID 39768960, 2024). "PTH can affect the secretion and transport of uric acid and lead to hyperuricemia." (PMID 36583002, 2022). "Such an association may be further supported by the observations that recombinant PTH may induce hyperuricemia and parathyroidectomy reduces serum uric acid levels." (PMID 24340056, 2013). "Low level of vitamin D could leads to hyperuricemia from PTH stimulation." (PMID 26417870, 2015). "The use of cinacalcet, a calcimimetic drug that can reduce PTH levels, in these animals prevented the ABCG2 reduction and urate accumulation, suggesting a potential therapeutic approach to mitigate SHPT-induced hyperuricemia." (PMID 40710544, 2025). "PTH may downregulate the expression of the urate exporter ABCG2 in intestinal and renal and suppress the urate excretion, which in turn could lead to hyperuricemia." (PMID 36583002, 2022). "Kidney dysfunction entails secondary parathyroidism, and increased levels of parathyroid hormone (PTH) seem to play a crucial role in regulation of the major urate transporter in the gastrointestinal tract, i.e., BCRP, leading to clinically observed hyperuricemia." (PMID 32715435, 2020). "Conversely, hyperuricemia promotes CKD progression via vascular, inflammatory, and fibrotic pathways, exacerbating mineral disturbances such as phosphate retention, hypocalcemia, and reduced vitamin D activation, thereby promoting PTH secretion and parathyroid hyperplasia and resulting in SHPT." (PMID 40710544, 2025). "Additional biochemical findings can include hypocitraturia, increased parathyroid hormone (PTH) levels (independent of GFR), and hyperuricaemia." (PMID 24321194, 2013).